IL6 (interleukin 6)
Diseases named in the same sentence as IL6 in open-access papers (continued):
Sharing a sentence is not in itself a finding about the gene and the disease.
hematoma (continued). "Exploratory factor analysis indicated two major underlying immunological processes expressed by the cytokines in both blood and hematoma fluid, but with a different pattern and particularly regarding the cytokines IL-13, IL-6, IL-4 and TNF-α." (PMID 24587250, 2014). "Compared with other hematoma types, the separated type of hematoma had significantly higher concentrations of fibrinogen, fibrin monomer, D dimer, interleukin-6, and interleukin-8, which indicates a higher tendency to rebleed, hyperfibrinolytic activity, and more severe inflammatory response." (PMID 36338617, 2022). "We also used ELISAs to test the levels of IL-6, IL-8 and IL-10 in the capsule of the hematoma." (PMID 34813498, 2021). "In addition, there were higher concentrations of IL-6, IL-8, and IL-10 in the hematoma fluid than in the serum." (PMID 34813498, 2021). "IL-6 can increase the gap between vascular endothelial cells and thus increase the permeability of blood vessels, suggesting that the inflammatory response is an important factor that leads to hematoma growth and recurrence." (PMID 32010057, 2019). "However, we found that the proinflammatory cytokine IL-6 in the hematoma fluid was significantly higher than that in the peripheral venous blood [(3365.8 ± 863.7) pg/ml vs. (58.6 ± 14.6) pg/ml, p = 0.00]." (PMID 32010057, 2019). "However, the D-dimer contents which reflect the severity of fibrinolysis in the hematoma and the proinflammatory cytokine interleukin 6 (IL-6) were significantly higher in the hematoma fluid than in the peripheral venous blood." (PMID 32010057, 2019). "Therefore, the first aim of this study was to conduct multiplex cytokine analysis in blood and fracture hematoma of sham- and OVX-mice to investigate whether further cytokines in addition to Mdk and IL-6 are affected by estrogen-deficiency." (PMID 30013010, 2018). "However, if vasospasm is caused not by direct mechanical or hematoma stimulation, but by inflammatory cytokines - including IL-6 - induced by surgical stress, there is a possibility that a delayed onset of vasospasm may develop." (PMID 40970012, 2025). "The hematoma phase is characterized by the release of pro-inflammatory cytokines such as interleukin-1 (IL-1), tumor necrosis factor alpha (TNF-α), and interleukin-6 (IL-6), which recruit neutrophils and macrophages to the fracture site." (PMID 41008976, 2025). "External drainage of the drill hole in patients with CSDH can reduce the levels of IL6/8/10 and VEGF, as well as other cytokines in the hematoma fluid." (PMID 38914867, 2024). "The WB results showed that after treatment with UA, the levels of IL-6 and TNF-α in the brain tissues around the hematoma were significantly decreased." (PMID 37834220, 2023). "The expression levels of IL-1β, IL-6 and TNF-α in the serum and fracture end hematoma samples of the 48 patients were statistically analyzed, and univariate linear regression analysis was performed." (PMID 37038178, 2023). "Meanwhile, IL-1β and IL-6 returned to basal levels, and the level of TNF-α in the peri-hematoma region was even lower than that in the control group at 7 days post-ICH, indicating a reaction to the continued immune response." (PMID 36792604, 2023). "Laboratory analysis showed that the relative expression levels of IL-1β, IL-6, and TNF-α in the hematoma at the fracture end were 1.0177, 1.0227, and 1.0095, respectively." (PMID 37038178, 2023). "The levels of IL-1β, IL-6 and TNF-α in the serum and fracture end hematoma samples of the two groups were recorded, and their means were compared by independent sample t test." (PMID 37038178, 2023). "The relative expression of IL-1β, IL-6, and TNF-α in the fracture end hematoma samples was positively correlated with the corresponding levels of these immune factors in the serum samples." (PMID 37038178, 2023).
hematoma (continued). "The expression levels of the three immune factors (IL-1β, IL-6 and TNF-α) in the fracture end hematoma samples were significantly positively correlated with those in the serum samples (P < 0.05)." (PMID 37038178, 2023). "Our analysis indicated that VEGF, PDGF-BB, TNF-alpha, MMP-9, IL-6, CCL2, IL-1 alpha, MMP-1, MMP-8, and IL-8 were DEGs between the hematoma fluid and the peripheral blood before surgery." (PMID 35207175, 2022). "Clinical studies have reported associations between serum inflammatory markers in the acute phase of ICH, mainly CCL2, CXCL10, IL-6, IL-11, CRP, fibrinogen, and CSF cytokines with hematoma expansion and early neurological decline." (PMID 34439789, 2021). "Murine intracerebral hemorrhage models exposed to Cerebrolysin revealed significant reductions in pro-inflammatory markers such as IL-β, IL-6 and TNF-α as well as aquaporin-4, an important mediator for hematoma-induced vasogenic edema." (PMID 33143640, 2020). "CSDH significantly increases the level of IL-6, IL-8 and TNF-α in the hematoma membrane and its boundary brain tissue on days 3 and 21 after CSDH formation compared to rats subjected to sham surgery." (PMID 31595197, 2019). "In particular, the cytokines IL-13, IL-6, IL-4 and TNF- α exhibited differences in loadings between an exploratory factor analysis from blood and hematoma samples." (PMID 24587250, 2014). "IL-6 secretion, as well as expression, showed a trend towards higher occurrence in smokers’ hematomas; nevertheless, results were not significant." (PMID 35621464, 2022). "Compared with the sham group, TNF-α, IL-6, and IL-10 in hematoma increased significantly in the CSDH group (TNF-α: 26.51 ± 5.35 vs 250.31 ± 26.99 pg/ml, P < 0.01; IL-6: 25.76 ± 6.39 vs 112.77 ± 6.91 pg/ml, P < 0.01; IL-10 : 17.60 ± 1.53 vs 82.76 ± 8.12 pg/ml, P < 0.01." (PMID 32328124, 2020). "The principal component analysis indicated that many cytokines related to inflammation and activated immune system (myeloperoxidase, Il-6, Il-8 and MCP-1) as well as many angiogenic factors (angiopoetin-2, VEGF-A) were found to be significantly more expressed in hematoma." (PMID 32325892, 2020). "At 2 days post-bleed, IL-10 levels correlate with IL-6 levels, and IL-6 levels correlate with hematoma volume and mass effect, but IL-10 does not." (PMID 28659854, 2017). "Since the cytokines IL-13, IL-6, IL-4 and TNF-α in particular displayed a different loading pattern in blood compared to hematoma fluid samples, they could play a different role in the local inflammatory response in the hematoma compared with the systemic response assessed in blood samples." (PMID 24587250, 2014). "There were statistically significant differences between the concentrations of IL6/8/10 and VEGF in preoperative venous blood and intraoperative hematoma fluid without saline washing in the observation group and the control group." (PMID 38914867, 2024). "At the fracture site (hematoma), there were no major alteration in levels of CXCL-1, IL-6, and MCP-1 except for MIP-1α that was higher by trend in GRdim compared to wild type mice in the context of combined trauma." (PMID 33679723, 2020). "Similar to our data, increased IL1-beta, IL6 and IL8 (protein levels) were detected early in hematoma while we did not see a clear increase in IL10, IL1R or VEGF early (although at mRNA levels rather than protein)." (PMID 32054088, 2020). "The IL-6 and CXCL8 in blood samples and CCL2, IL-5 and IL-13 in hematoma samples did not have significant standardized loadings, and were therefore excluded from the statistical models." (PMID 24587250, 2014). "The concentrations of IL6/8/10 and VEGF in the drainage fluid before extubation were still high; however, compared with the levels in the hematoma fluid obtained without saline washing, they had been greatly reduced, and the comparison of the two values was statistically significant." (PMID 38914867, 2024).
scleroderma (38 papers, 2009 to 2025). Scleroderma is a rare autoimmune connective tissue disorder characterized by abnormal hardening of the skin and, sometimes, other organs. "In a bleomycin-induced scleroderma model, IL-6 deficiency in B cells can reduce skin fibrosis, while IL-10 deficiency in B cells can increase skin fibrosis." (PMID 39080112, 2024). "Taxane drugs, such as paclitaxel and docetaxel, have been associated with scleroderma-like lesions that exhibit unique pathophysiological pathways, including elevated serum interleukin-6 levels, with docetaxel exhibiting more pronounced effects." (PMID 39064521, 2024). "Recently, we have demonstrated that serum-derived IgG fractions from patients with scleroderma-associated renal crisis stimulate interleukin-6 (IL-6) production by targeting the protease-activated receptor 1 (PAR1) on ECs." (PMID 37965310, 2023). "IL-6 is a well-established profibrotic cytokine whose elevated expression is associated with severity of scleroderma skin fibrosis." (PMID 37669366, 2023). "In summary, we were able to demonstrate that blocking CD47 and IL-6 prevented the loss in fat tissue during disease initiation, reversed fibrotic skin changes thereafter, and eliminated human scleroderma fibroblasts in an adaptive transfer model." (PMID 32814713, 2020). "The involvement of both TLR-2 and TLR-3 in scleroderma is highly probable since SSc fibroblasts that overexpress these types of receptors produce an increased amount of IL-6, a crucial molecule in the fibrotic process." (PMID 38892733, 2024). "MISTRG6 mice transplanted with scleroderma skin demonstrated multiple fibrotic responses centred around human IL‐6 signalling, which was improved by the presence of healthy bone marrow‐derived immune cells." (PMID 38577035, 2024). "In sum, through the retention of human T cells in scleroderma skin, scleroderma skin grafts to humanized mice permitted identification of IL-6 trans-signaling as a T cell–regulated process in scleroderma pathogenesis." (PMID 37669366, 2023). "Our results highlight the importance of IL-6 trans-signaling in pathogenesis of scleroderma and the ability of healthy bone marrow–derived immune cells to mitigate disease." (PMID 37669366, 2023). "In scleroderma skin, expression of human IL-6 corresponds with multiple pathologic features including T cell activation and ECM expression." (PMID 37669366, 2023). "More studies are required to fully understand regulation of IL-6 expression in scleroderma skin grafts." (PMID 37669366, 2023). "The hypoxia caused by vasculopathy, which plays a major role in the pathogenesis of scleroderma, affects the transcription of IL-6 gene in PSS." (PMID 37670355, 2023). "In MISTRG6 humanized mice, improvement in fibrosis of scleroderma skin grafts correlated with reduced expression of human IL-6." (PMID 37669366, 2023). "Elevated expression of human IL-6 thus links the T cell and mesenchymal changes characteristic of fibrotic scleroderma skin." (PMID 37669366, 2023). "We therefore assessed the effects of HSC engraftment on human IL-6 expression in the scleroderma xenografts." (PMID 37669366, 2023). "Scleroderma patients display significantly higher IL6 production by B cells, and suppression of B cell-derived IL6 was attributed to cell contact between iNKT and CD1d-expressing B cells via the CD1d-TCR axis." (PMID 36119077, 2022). "Similar results were acquired in scleroderma pathogenesis that involved the fibroblast transdifferentiation inhibition and over-expression of IL-6 in scleroderma cultures." (PMID 34205169, 2021). "Therapeutically, combined CD47 and IL-6 blockade reversed skin fibrosis in mice and led to the rapid elimination of ectopically transplanted scleroderma cells." (PMID 32814713, 2020). "In this study, we evaluated the efficiency of the “don’t-eat-me-signal” CD47 either alone or in combination with an IL-6 inhibitor in a scleroderma mouse model." (PMID 32814713, 2020).
scleroderma (continued). "Because our results had shown that both hedgehog signaling and IL-6 contributed to scleroderma, we combined both immune therapies either with vismodegib (CD47/PD-L1 inhibition + vismodegib) or with the IL-6 inhibitor tocilizumab (CD47/IL-6 inhibition)." (PMID 32814713, 2020). "Combined CD47 and IL6 inhibition eliminates diseased fibroblasts and reverses skin fibrosis in a murine scleroderma model." (PMID 32814713, 2020). "In accordance with these findings, CD47/IL-6 blockade accelerated the elimination of human scleroderma fibroblasts and increased apoptosis in an adaptive transfer model." (PMID 32814713, 2020). "The novelty of our findings is that they not only support that IL-6 and E2 are interrelated in the skin, but also that they function together, contributing to the pathogenesis of dermal fibrosis in the hormonal and inflammatory scleroderma microenvironment." (PMID 39000334, 2024). "Although the exact pathogenesis of scleroderma is unknown, a couple of cells and cytokines are known to be involved in the process of fibrosis in this disease, e.g. Interleukin 6 (IL-6) released by inflammatory cells." (PMID 37670355, 2023). "Our scleroderma skin grafts to humanized mice support IL-6 trans-signaling as a key driver of skin fibrosis in pansclerotic morphea and align our results with recent identification of STAT4 mutations driving IL-6 expression in the childhood form of pansclerotic morphea." (PMID 37669366, 2023). "Thus, MISTRG6 mice transplanted with scleroderma skin demonstrated multiple fibrotic responses centered around human IL-6 signaling, which was improved by the presence of healthy bone marrow–derived immune cells." (PMID 37669366, 2023). "To evaluate how IL-6 signaling may drive fibrosis in scleroderma skin grafts, we investigated the effects of T cell activation on expression of MHC class II and IL6 receptor alpha subunit (IL6Ra)." (PMID 37669366, 2023). "Thus, IL-6 trans-signaling appears to be a fundamental component driving fibrosis in our humanized mouse model of scleroderma." (PMID 37669366, 2023). "IL-6 levels can be used to identify all stages and severity of scleroderma (SSc)." (PMID 37449201, 2023). "The importance of IL-6 trans-signaling was further supported by our in vitro studies of SSc fibroblasts derived from patients with limited cutaneous SSc, suggesting IL-6 as a commonly dysregulated signaling pathway in multiple scleroderma subsets." (PMID 37669366, 2023). "Additionally, the IL-6 promoter was more readily accessible, a finding that corresponds with a recent study in which IL-6 activated profibrotic pathways in explanted scleroderma samples." (PMID 32814713, 2020). "CD47/IL-6 inhibition eliminates scleroderma fibroblasts in an adaptive transfer model." (PMID 32814713, 2020). "However, the loss of fat tissue with stiffening of the skin is a hallmark of scleroderma, and CD47/IL-6 increased the dermal fat content." (PMID 32814713, 2020). "Finally, we evaluated if CD47/IL-6 inhibition accelerates the elimination of transplanted human scleroderma fibroblasts in an adaptive transfer model." (PMID 32814713, 2020). "Moreover, the presence of healthy human immune cells in scleroderma skin grafts may act as a sink for IL-6 protein and disrupt a positive feedback loop, such as been described for IL-6 and IL-17A." (PMID 37669366, 2023). "Regulation of IL-6 expression is highly complex, so multiple mechanisms may explain how healthy bone marrow–derived immune cells could down-regulate IL-6 expression in scleroderma skin grafts." (PMID 37669366, 2023). "Th17 cells and pro-inflammatory cytokines such as IL-1β, IL-6, IL-17, and TNF-α play important roles in the pathogenesis of scleroderma." (PMID 33947424, 2021). "IL-6, IL-13, IL-17, and TNF-α are cytokines recognized to be involved in the pathophysiology of scleroderma." (PMID 34445632, 2021).
scleroderma (continued). "Altogether, our study demonstrates the efficiency of combining different immunotherapies in treating scleroderma and provides a rationale for combining CD47 and IL-6 inhibition in clinical trials." (PMID 32814713, 2020). "In particular, endothelial incubation with SSc-ICs modulates several molecules involved in the three cardinal scleroderma pathophysiologic processes: vascular dysfunction (ET-1 and IL-8), inflammation (ICAM-1, IL-6), and fibrosis (TGF-β1)." (PMID 33168071, 2020). "In addition, we evaluated the relevant infoammatory cytokines of IL1, IL6, IL12,TNFα, and CXCL12 in the normal, scleroderma and treatment groups, respectively." (PMID 35315234, 2022). "In particular, the incubation with SSc-ICs modulated several molecules involved in the three cardinal scleroderma pathophysiologic processes: vascular dysfunction (ET-1 and IL-8), inflammation (ICAM-1, IL-6, IFNs and MCP-1) and fibrosis (TGF-β1 and Pro-CollagenIα1)." (PMID 30157947, 2018). "Treatment with IL-6-neutralizing antibodies prior to manifestations of scleroderma significantly decreased disease severity, while no reduction was observed when IL-6 neutralization was started after the onset of cGVHD." (PMID 28642760, 2017). "Various mechanisms of action have been proposed for scleroderma, particularly the role of innate and adaptive immune systems in upregulating profibrotic and proinflammatory cytokines, such as transforming growth factor beta (TGF-β) and interleukin-6 (IL-6), respectively." (PMID 40861533, 2025). "We found that HUMSCs-Ex elevated M1 macrophage markers (IL-6, IL-12p40, iNOS) and inhibited M2 macrophage markers (IL-4, IL-10, Arg-1 and CD206) in a mouse model of scleroderma, thus suggesting that HUMSCs-Ex might play an antifibrotic role by regulating the M1/M2 macrophage balance." (PMID 34784013, 2022). "Moreover, studies in a scleroderma model demonstrate stimulation of B cells with the ECM component hyaluronan activates TLR2 and TLR4 and results in inflammatory cytokine secretion, including IL-6, TNFα, and IFNγ." (PMID 34381449, 2021). "Regarding the good safety profiles of currently available CD47- and IL-6–blocking agents, we believe that our study gives enough evidence to safely try combined immunotherapy with CD47 and IL-6 inhibition in patients with highly fibrotic and stable, nonprogressive scleroderma." (PMID 32814713, 2020).